C8orf88 (chromosome 8 open reading frame 88)
Tractability: No criterion of Open Targets' tractability assessment is met for any kind of drug.
Gene: Protein-coding gene on chromosome 8 (90,958,084 to 90,985,238, reverse strand). Ensembl gene ENSG00000253250.
Subcellular location (Human Protein Atlas): Cytosol; Golgi apparatus
Gene Ontology:
Molecular function: eukaryotic initiation factor 4E binding; translation repressor activity
Biological process: negative regulation of translational initiation
Genetic constraint (gnomAD): Loss-of-function variants: 1 observed, 0.8 expected, observed/expected ratio (o/e) 1.26, 90% interval 0.29 to 1.91. That is too few expected variants to judge how well the gene tolerates losing a copy. Missense variants: 20 observed, 22.93 expected, observed/expected ratio (o/e) 0.87, 90% interval 0.61 to 1.27. Synonymous variants: 7 observed, 7.88 expected, observed/expected ratio (o/e) 0.89, 90% interval 0.5 to 1.62.
Homologues: Orthologues: chimpanzee C8H8orf88 (100% identical), macaque C8H8orf88 (99% identical), pig C8orf88 (96% identical), dog C8orf88 (95% identical), mouse Gm11837 (95% identical), rat C5h8orf88 (91% identical).
Diseases named in the same sentence as C8orf88 in open-access papers:
C8orf88 is named in the same sentence as 5 diseases in open-access papers, as found by Europe PMC text mining. Sharing a sentence is not in itself a finding about the gene and the disease. The quoted sentences say what the papers report.
viral infection (1 paper, 2021). "Interestingly, many of the candidate proteins have only limited functional links to viral infection and immune regulation and were not previously known to interact with NAs (e.g., c8orf88, DTYMK, KIF2A, PDAP1, PDIA5, TAOK1, TAOK2, and VRK1)." (PMID 34853303, 2021).
viral meningitis (1 paper, 2024). Inflammation of the membranes surrounding the brain and spinal cord due to a viral infection. "In viral meningitis subjects, the ceRNA network was composed of hsa-miR-199b-5p, 4 mRNAs (ANKRD22, EVI2A, USP15, and C8orf88), and AC002511.1." (PMID 38347610, 2024).
cancer (2 papers, 2023). A tumor composed of atypical neoplastic, often pleomorphic cells that invade other tissues. "Given the extensively characterized role of 4E-BP1 dysregulation across many malignancies, and the mapping of C8ORF88 expression to the germ cells of testes, C8ORF88 might play a role in tumorigenesis and disease progression in cancers of germ cell origin." (PMID 38003019, 2023).
tumor (2 papers, 2023 to 2025). "In this study, it was demonstrated that the expression of C8orf88 was negatively correlated with immune cells and anti-tumor cells, while it was positively correlated with immune suppression and tumor development." (PMID 40777025, 2025). "LINC00702, C8orf88, and FILP1, upregulated in diffuse-type GC, promoted tumor progression and metastasis through immune suppression and activation of tumor-promoting pathways." (PMID 40777025, 2025).
C8orf88 also shares sentences with these, for which no sentence is quoted: prostate carcinoma (1 paper).